MIR6778 (microRNA 6778)
Synonyms: hsa-mir-6778
Gene: MicroRNA gene on chromosome 17 (18,340,814 to 18,340,886, reverse strand). Ensembl gene ENSG00000283772.
Homologues: Orthologues: chimpanzee MIR6778 (100% identical).